ZNF451 (zinc finger protein 451)
Description:
E3 SUMO-protein ligase; has a preference for SUMO2 and SUMO3 and facilitates UBE2I/UBC9-mediated sumoylation of target proteins. Plays a role in protein SUMO2 modification in response to stress caused by DNA damage and by proteasome inhibitors (in vitro). Required for MCM4 sumoylation (By similarity). Has no activity with SUMO1. Preferentially transfers an additional SUMO2 chain onto the SUMO2 consensus site 'Lys-11'. Negatively regulates transcriptional activation mediated by the SMAD4 complex in response to TGF-beta signaling. Inhibits EP300-mediated acetylation of histone H3 at 'Lys-9'. Plays a role in regulating the transcription of AR targets.
Synonyms: COASTER; KIAA0576; KIAA1702; dJ417I1.1; ZATT
Tractability: PROTAC: UniProt records ubiquitination sites on it; ubiquitination databases record sites on it; its protein half-life has been measured.
Gene: Protein-coding gene on chromosome 6 (57,086,844 to 57,170,305, forward strand). Ensembl gene ENSG00000112200.
Subcellular location: Nucleus; Nucleus, PML body; Nucleus, nucleoplasm
Subcellular location (Human Protein Atlas): Nucleoplasm
Gene Ontology:
Molecular function: protein binding; SUMO ligase activity; transcription corepressor activity; transcription regulator inhibitor activity; DNA-binding transcription factor activity, RNA polymerase II-specific; sequence-specific DNA binding
Biological process: negative regulation of transcription initiation by RNA polymerase II; negative regulation of transforming growth factor beta receptor signaling pathway; protein sumoylation
Cellular component: nucleus; PML body; nucleoplasm
Genetic constraint (gnomAD): Loss-of-function variants: 68 observed, 91.94 expected, observed/expected ratio (o/e) 0.74, 90% interval 0.61 to 0.9. The upper end of that interval is the gene's LOEUF score, 0.9, which puts it in group 3 of 6, group 1 being the genes least tolerant of losing a copy. Missense variants: 1,000 observed, 1,185.2 expected, observed/expected ratio (o/e) 0.84, 90% interval 0.8 to 0.89. Synonymous variants: 334 observed, 401.15 expected, observed/expected ratio (o/e) 0.83, 90% interval 0.76 to 0.91.
Homologues: Orthologues: chimpanzee ZNF451 (99% identical), macaque ZNF451 (97% identical), dog ZNF451 (88% identical), rabbit ZNF451 (87% identical), guinea pig ZNF451 (82% identical), mouse Zfp451 (79% identical), pig ZNF451 (78% identical), rat Zfp451 (73% identical), tropical clawed frog znf451 (49% identical). Paralogues in human: PRDM10 (9% identical), ZNF148 (8% identical), PATZ1 (8% identical), MTF1 (8% identical), ZNF281 (8% identical), PRDM1 (8% identical), ZBTB7C (8% identical), ZNF143 (8% identical), ZNF384 (7% identical), ZNF76 (7% identical), ZBTB16 (7% identical), ZNF362 (7% identical), and 24 more.